PRODH (proline dehydrogenase 1)
Diseases named in the same sentence as PRODH in open-access papers (continued):
Sharing a sentence is not in itself a finding about the gene and the disease.
cancer (68 papers, 2008 to 2025). A tumor composed of atypical neoplastic, often pleomorphic cells that invade other tissues. "During stress situations (e.g., genotoxic, inflammatory, metabolic as oxygen or glucose deficiency), PRODH/POX is up-regulated in cancer cells and evoke pro-survival activity, both in vitro and in vivo." (PMID 33818628, 2021). "Moreover, significant association was identified between PRODH expression and immune infiltration in 18 cancers, of which 8 showed positive association and 10 showed negative association." (PMID 37564635, 2023). "In addition, the PRODH gene-encoding PRODH, a mitochondrial enzyme degraded by proline, regulates cancer cell survival and apoptosis." (PMID 37564635, 2023). "Therefore, this study aims to delineate the association between SCZ-related genes (HTR2A, COMT, PRODH) and different cancers." (PMID 37564635, 2023). "Hence, here in this article, we aim to elucidate the intricate mechanisms underlying the dual role of PRODH in cancer." (PMID 38023181, 2023). "SCZ-associated genes (HTR2A, COMT, and PRODH) were subjected to pan-cancer analysis." (PMID 37564635, 2023). "This high number of early apoptotic and dead cells in the MCF7POK-KO control might underline the pro-survival role of PRODH/POX in cancer cells." (PMID 35409177, 2022). "Notably, the role of PRODH has been implicated in various cancers." (PMID 33202765, 2020). "PRODH is a target of inhibitor discovery because of its role in the metabolism of certain cancer cells." (PMID 39598797, 2024). "Proline dehydrogenase (PRODH), an enzyme that catalyzes proline catabolism, and proline degradation products by PRODH, such as ATP and ROS, are known to play a critical role in cancer progression." (PMID 38785550, 2024). "Patients with PRODH-positive tumors had better cancer-free specific and overall survival compared to those with negative tumors." (PMID 38255788, 2024). "Moving forward, the development and application of appropriate technical means to more thoroughly study the role of PRODH in cancer will be crucial." (PMID 38023181, 2023). "Most studies have indicated that these ligands can not only activate the PRODH promoter but also upregulate PRODH expression and subsequently promote apoptosis in cancer cells by increasing ROS." (PMID 38023181, 2023). "Some reports suggest that the function of PRODH as either a protumor factor or a suppressor of cancer can vary depending on the cancer types and the metabolic context." (PMID 38023181, 2023). "On the other hand, in some contexts, such as hypoxia, PRODH can also function as an oncogene by promoting cancer cell survival, growth, and metastasis." (PMID 38023181, 2023). "Nonetheless, searching for pharmacological compounds that can target PRODH for cancer-targeted therapy is still of great importance." (PMID 38023181, 2023). "For instance, PRODH induces apoptosis and senescence through ROS signaling in different types of cancers, while as a protumor factor, PRODH promotes malignant phenotypes of certain tumors under stresses such as hypoxia." (PMID 38023181, 2023). "On the other hand, notable up-regulation of PRODH was observed in 5 cancers(UCEC、HNSC、KIRC、PAAD、TGCT)." (PMID 37564635, 2023). "The correlation between TMB and HTR2A, COMT, and PRODH was examined for each cancer using Spearman’s correlation method." (PMID 37564635, 2023). "This study explored the expression of SCZ-related genes (HTR2A, COMT, and PRODH) in pan-cancer analysis." (PMID 37564635, 2023). "Nevertheless, these results provided insight into the complexity of the molecular mechanisms creating PRODH/POX-dependent and PRODH/POX-independent apoptosis in cancer cells." (PMID 35409177, 2022).
cancer (continued). "Although several mechanisms for down-regulation of PRODH/POX were described, the elevation of proline concentration in cancer cells is attributed to an increased degradation of type I collagen in the extracellular matrix." (PMID 35733940, 2022). "Previous studies have reported that, under nutrient stress, cancer cells catabolize proline to generate ATP via the first step of its degradation by proline oxidase (PRODH)." (PMID 35888705, 2022). "It seems that metformin-dependent inhibition of collagen biosynthesis and metformin-induced PRODH/POX expression accelerates the proline cycle, contributing to ROS generation and apoptosis in cancer cells." (PMID 35216470, 2022). "Studies of last decade provided several lines of evidence for regulatory role of proline availability for PRODH/POX-dependent apoptosis/autophagy in cancer cells." (PMID 33818628, 2021). "It has been found that PRODH/POX induces apoptosis in several cancer cell types by intrinsic or extrinsic pathway." (PMID 34944532, 2021). "It seems interesting from a cancer therapy point of view to inhibit proline metabolism by targeting PRODH/POX and PYCR1 and interfering with metastasis formation." (PMID 34451829, 2021). "A downregulation of PRODH/POX also occurs in kidney and digestive tract cancers, contributing to cancer development and progression." (PMID 34577574, 2021). "PPARγ was found to upregulate PRODH/POX expression, accompanied by ROS generation in several cancer cell lines." (PMID 33818628, 2021). "The understanding of the mechanism for the differential PRODH/POX-dependent functions is one of the challenges in cancer cell biology." (PMID 33818628, 2021). "Our findings are important not only in proving a celecoxib-based strategy to inhibit cancer growth but also in supporting the concept of a PRODH/POX-dependent mechanism of celecoxib anticancer activity." (PMID 34577574, 2021). "It was reported that cancer cells accumulate proline in higher concentrations than healthy cells providing substrate for PRODH/POX activity." (PMID 34577574, 2021). "It was found that proline metabolism and proline dehydrogenase/proline oxidase (PRODH/POX) has the main role in the modulation of cancer cell survival/apoptosis." (PMID 33858433, 2021). "The role of PRODH-mediated Proline oxidation in the proliferation/survival of cancer cells has been exhaustively described elsewhere." (PMID 32500033, 2020). "Obtained results indicated a significant increase in PRODH/POX expression in cancer cells after incubation with various concentrations of celecoxib compared to controls." (PMID 31935820, 2020). "Studies of last decade provided several lines of evidence for the regulatory role of proline availability in PRODH/POX-dependent apoptosis/autophagy in cancer cells." (PMID 31933109, 2020). "These phenotypic changes were associated with elevated intracellular proline abundance, when either PYCR1 was silenced or cancer cells were treated with the PRODH inhibitor THFA." (PMID 33109600, 2020). "Base on this mechanism, the role of PRODH/POX in the regulation of cellular metabolism has recently studied as an approach to cancer treatment." (PMID 31933109, 2020). "PRODH/POX acting as a driver of apoptosis was clearly evaluated in a model of PRODH/POX knockdown cancer cells." (PMID 31933109, 2020). "Considering the crucial role of proline metabolism and proline dehydrogenase/proline oxidase (PRODH/POX) in the regulation of cancer cell survival/apoptosis, we studied these processes in polyphenol-treated CAL-27 cells." (PMID 29681859, 2018). "For instance, glucose depletion enhances PRODH/POX expression through AMPK to promote cancer cell survival through autophagy." (PMID 29568391, 2018). "Therefore, POX/PRODH is believed to play a dual, context-dependent role, being either pro-cancer or pro-apoptotic." (PMID 38275897, 2024).
cancer (continued). "Several studies document that PRODH is dysregulated in different types of cancer." (PMID 38255788, 2024). "Also, mechanism-based inactivators that covalently modify the FAD of PRODH show activity in cancer cells." (PMID 39598797, 2024). "The role of PRODH in cancer is complicated and depends on cancer type and tumor microenvironment." (PMID 39598797, 2024). "Therefore, it has been reported that PRODH plays important roles in apoptosis, senescence, and cancer treatment via cellular redox control." (PMID 38480845, 2024). "Proline dehydrogenase (PRODH), an enzyme catalyzing proline catabolism, and the degradation products of proline by PRODH, such as ATP and ROS, are known to play critical roles in cancer progression." (PMID 38023181, 2023). "Interestingly, compared to the unambiguous promoting effect of PYCR on tumorigenesis and cancer progression, PRODH plays a dual role in cancer." (PMID 38023181, 2023). "In order to assess whether PRODH can serve as a novel target for cancer therapy, we will provide an overview of the biological functions of PRODH and its double-edged role in cancer in this article." (PMID 38023181, 2023). "In summary, the proapoptotic effect of PRODH on cancer cells is primarily determined by the activation of upstream signaling pathways that induce high expression levels of PRODH and inhibition of collagen synthesis to provide adequate proline for PRODH-mediated ROS generation." (PMID 38023181, 2023). "Notably, a study conducted on the effect of celecoxib on oral squamous cell carcinoma suggests that celecoxib treatment triggers apoptosis of cancer cells by upregulating the expression of PRODH." (PMID 38023181, 2023). "Furthermore, another great challenge is that treatment strategies targeting PRODH require modifications depending on the type of cancer and metabolic context." (PMID 38023181, 2023). "Furthermore, glucose deprivation increases the levels of intracellular proline and PRODH expression levels in cancer cells, leading to further activation of the pentose phosphate pathway." (PMID 38023181, 2023). "However, based on our previous studies, the role of PRODH/POX in the apoptosis/survival of cancer cells is not only a zero–one system but rather depends on the metabolic context of the specific cell type." (PMID 35409177, 2022). "Proline availability for PRODH/POX could be important factor in the creation of a pro-apoptotic phenotype of cancer cells." (PMID 35409177, 2022). "However, in several of our previous studies, we found that the role of PRODH/POX in the apoptosis/survival of cancer cells depends on the metabolic context of a specific cell type." (PMID 35733940, 2022). "In many types of cancer, PRODH acts as oncogene to promote cancer occurrence and progression." (PMID 35386280, 2022). "It has been considered that proline availability for PRODH/POX could be an important factor in the creation of pro-apoptotic phenotype of cancer cells." (PMID 35733940, 2022). "However, in cancer cells, proline metabolism by PRODH/POX is limited, since lactate inhibits its activity." (PMID 35216470, 2022). "Therefore, we suggest that the role of PRODH/POX in apoptosis/survival in cancer cells is metabolic context-dependent and the process occurs through various mechanisms in different types of cancer cells." (PMID 35409177, 2022). "This knowledge led us to hypothesize that up-regulation of prolidase and PRODH/POX with inhibition of collagen biosynthesis may represent potential pharmacotherapeutic approach to induce apoptosis or autophagic death in cancer cells." (PMID 33818628, 2021). "Whether up-regulation of PRODH/POX at proline availability in cancer cells could contribute to apoptosis requires to be explored." (PMID 33818628, 2021). "Therefore, cancer cell reprograms its function to decrease the rate of collagen biosynthesis and make proline available for PRODH/POX activity." (PMID 34451829, 2021).
cancer (continued). "However, up-regulation of PRODH/POX expression in cancer cells is counteracted by inhibitory effect of succinate (TCA metabolite) and lactate (metabolite of Warburg effect) on this enzyme." (PMID 33818628, 2021). "The knowledge on functional significance of proline and collagen metabolism in complex metabolic regulatory mechanisms may contribute to understanding differential PRODH/POX-dependent functions (apoptosis/autophagy/survival) in cancer cells." (PMID 33818628, 2021). "However, in conditions of nutrient availability, silencing of PRODH/POX also induced pro-survival phenotype of cancer cells." (PMID 33818628, 2021). "It has been suggested that up-regulation of PRODH/POX by PPAR-gamma ligands could induce apoptosis in cancer cells." (PMID 34944532, 2021). "Understanding the interplay between key amino acids and TCA/Urea metabolites and their role in the regulation of PRODH/POX-dependent apoptosis/autophagy might be a promising approach to targeted cancer therapy." (PMID 31933109, 2020). "All together these findings support the idea that the pro- or anti-survival roles of PRODH in cancer cells may be context/environment- and cell type- dependent." (PMID 32500033, 2020). "PRODH expression is induced under hypoxic conditions in different tumor cell lines and in a mouse xenograft model of human breast tumor, and contributes to cancer cell survival by inducing autophagy." (PMID 32500033, 2020). "It was shown that c-MYC could not only inhibit POX/PRODH expression primarily through increasing miR-23b* but also evidently increase the biosynthesis of proline from glutamine, maintaining cancer cell survival and proliferation." (PMID 33117704, 2020). "It was reported that targeting PRODH activity could have the potential to be effective against cancer cells and micrometastases." (PMID 30545412, 2018). "Recent data showed down-regulation of PRODH/POX expression in various type of cancer." (PMID 29568391, 2018). "It seems that PRODH/POX-dependent inhibition of HIF-1α could play important role in inhibition of cancer cell growth and invasion." (PMID 29568391, 2018). "However, proline degradation by PRODH/POX was found to induce apoptosis in several cancer cell lines." (PMID 29681859, 2018). "The mechanism of PRODH/POX-dependent inhibition of cancer cell proliferation may undergo through modulation of cell signaling pathways." (PMID 29568391, 2018). "PRODH plays a key role in apoptotic cell death, and autophagy in cancer cells." (PMID 30545412, 2018). "However PPAR-activated PRODH can also serve as a survival factor for cancer cells." (PMID 38023181, 2023). "Herein, a preliminary conclusion could be reached that the effect of SCZ-related genes HTR2A, COMT, and PRODH was highly variable in different cancers, and the prognostic significance of SCZ on cancer development needed to be explicitly explored for various cancers." (PMID 37564635, 2023). "PRODH/POX-dependent inhibition of cancer cell proliferation may result from ROS signaling." (PMID 35216470, 2022). "Therefore, PRODH/POX may play a dual role, but the mechanism that switches PRODH/POX from cancer growth-inhibiting to growth-supporting factor is unknown." (PMID 35216470, 2022). "However, PRODH/POX-mediated apoptosis could occur through different mechanisms in different cancer cells." (PMID 35733940, 2022). "Since cancer cells have high energy requirements and because of the Warburg’s effect glucose is not a sufficient source of energy, the cells require energy from protein degradation (mostly collagen), providing proline, among others, as a substrate for PRODH/POX resulting in ATP or ROS generation." (PMID 35409177, 2022).
cancer (continued). "Therefore, PRODH/POX may play dual role, but the mechanism that switches PRODH/POX from cancer cell growth inhibiting to growth supporting factor is unknown." (PMID 34944532, 2021). "However, the studies indicate that the pattern of PRODH/POX expression differs in various cancers." (PMID 34577574, 2021). "Therefore, the inhibition of PRODH by lactate indicates PRODH activity might be negatively affected in cancer cells." (PMID 33083024, 2020). "Therefore, it seems that down regulation of PRODH/POX may facilitate autophagy for cancer cell survival, while up-regulation of this enzyme may create condition for apoptosis." (PMID 29568391, 2018). "We found that both EZH2-A and -B subtypes inhibited the expression of these four downstream cancer related genes (BMP2, PRODH, FOXO4, NPRL2), while EZH2-C exhibited the opposite effect." (PMID 39850359, 2025). "In this work, immunohistochemistry data suggested that PRODH plays a role in lung tumorigenesis, particularly in the ADC subtype, where it appears to improve prognosis in terms of both cancer-specific survival and overall survival." (PMID 38255788, 2024). "After treating cancer cells with a synthetic AMPK activator, the activity of PRODH appears to have an increase." (PMID 38023181, 2023). "Overexpressing PRODH in NSCLC cells promotes EMT by facilitating migration and invasion of cancer cells." (PMID 38023181, 2023). "In 39 cancer types, including GBMLGG, HTR2A, COMT, and PRODH expressions were significantly correlated with immune cell infiltration." (PMID 37564635, 2023). "Compared with that in normal tissues, the expression of PRODH and PRODH2 was decreased in various cancer tissues, while that of P4HA and PYCR1 was increased in various cancer tissues." (PMID 36088469, 2022). "Several studies showed that in various cancers, PRODH/POX is down-regulated and the proline concentration is increased." (PMID 35733940, 2022). "The results presented in this report provide insight into the complexity of molecular mechanisms creating PRODH/POX-dependent and PRODH/POX-independent apoptosis in cancer cells." (PMID 35733940, 2022). "Therefore, PRODH/POX could be involved in anti-cancer activity of MET." (PMID 34944532, 2021). "Since PRODH/POX converts proline to glutamate and, then to α-ketoglutarate, it contributes to inhibition of HIF-1α transcriptional activity and limitation of cancer cell pro-survival properties." (PMID 34451829, 2021). "We have suggested that MET can stimulate apoptosis in cancer cells by a cascade of processes involving the induction of AMPK, PRODH/POX and ROS generation under proline availability determined by several proline utilization/supporting processes." (PMID 34944532, 2021). "In recent studies, it has been shown that the catabolic PRODH/POX pathway produces ATP for autophagy and reactive oxygen species (ROS) for apoptosis, which are both important for cancer progression." (PMID 33172086, 2020). "The results indicated a significant increase in PRODH/POX and PPARγ expression in cancer cells treated with various concentrations of celecoxib compared to controls." (PMID 31935820, 2020). "An important role of MYC in this process was previously reported in human cancer cell lines, where MYC inhibits PRODH and promotes the transcription of PYCR1 and ALDH18A1." (PMID 29132502, 2017). "Considering a threshold at ≥25% stained cancer cells, PRODH expression was elevated in NSCLC (36.3%) and was never observed in SCLC." (PMID 38255788, 2024).